IL4 (interleukin 4)
Diseases named in the same sentence as IL4 in open-access papers (continued):
Sharing a sentence is not in itself a finding about the gene and the disease.
asthma (continued). "In summary, administration of SCTE in this mouse asthma model significantly decreased the number of eosinophils in BALF and lung tissue, and reduced IL-4 IL-5, IL-13, TNF-α, and eotaxin production in BALF and total IgE and OVA-specific IgE levels in plasma after OVA challenge." (PMID 23244755, 2012). "As is known, IFN-γ was significantly increased, especially in the viral infection, but the role in asthma was not as clear as IL-4 and IL-17 until now." (PMID 22216085, 2011). "CD4+ T helper type 2 (TH2) cells, their cytokines IL-4, IL-5 and IL-13 and the transcription factor STAT6 are known to regulate various features of asthma including lung inflammation, mucus production and airway hyperreactivity and also drive alternative activation of macrophages (AAM)." (PMID 22014099, 2011). "IL-4 and -13 have been shown to induce AHR in mouse asthma models." (PMID 19641087, 2011). "IL-4 and IL-13 were shown to induce AHR in mouse asthma models." (PMID 21437195, 2011). "The replication of IL4 gene in children and adult cohorts implies its broader implication in asthma independent of development stages." (PMID 21387019, 2011). "Airway eosinophilia, together with Th2 cytokines IL-4, IL-5 and IL-13, may ultimately contribute to AHR in asthma." (PMID 21695271, 2011). "Despite these promising results, the clinical approaches towards asthma therapy by neutralizing IL-4, IL-5, or IL-13 frustrated the high expectations or did not progress to clinical trials." (PMID 20976014, 2010). "In the present study, we provided evidence that increased frequency of CD4+/IL-13+, but not CD4+/IL-4+ T cells was correlated with severity of asthma and these findings further suggest that IL-13 is a principal cytokine responsible for asthmatic symptoms." (PMID 21197090, 2010). "Regular treatment of patients with mild asthma with the long-acting β2-agonist formoterol does not decrease the number of IL-4 immunoreactive cells in their bronchial mucosa." (PMID 18315837, 2008). "Blocking IL-13, but not IL-4, in animal models of asthma prevents the development of airway hyperresponsiveness after allergen, despite a strong eosinophilic response." (PMID 18315837, 2008). "In an animal model of asthma there is increased IL-19 expression and transfer of the IL-19 gene into healthy mice up-regulated IL-4 and IL-5, but not IL-13, however, IL-19 up-regulated IL-13 in “asthmatic” mice." (PMID 18315837, 2008). "None of the well-defined asthma/inflammatory genes (Il1b, Il4, Il10, Il13, Il6, Tnfa, Infg, Tgfb1) are differentially expressed, although they connect many of the genes that are." (PMID 18087596, 2007). "Our study also rules out a requisite role for IL-4 in the TDI-ACD maternal effect, as IL-4KO mothers were able transmit asthma susceptibility to their offspring." (PMID 17662138, 2007). "The gene for IL-10, which is essential for the eosinophilic inflammation seen in asthma (and in this mouse model), is down-regulated, resulting in decreases in mucus production and eosinophilic inflammation without decreased IgE or IL-4." (PMID 18087596, 2007). "IL-4 production increased sharply in the cells from CRS-asthma patients, but not in the cells from asthma alone patients, or healthy controls and CRS alone patients." (PMID 16677400, 2006). "IL4 and IL10 has long been investigated as potential candidate genes for asthma and atopy." (PMID 16759385, 2006). "IL4/IL4RA pathway plays an important role in atopy and asthma." (PMID 16313681, 2005). "Individuals with antibodies against anti-Hsp60 and anti-Hsp70 were more likely to have a family history of asthma (p < 0.001) and higher plasma concentrations of total immunoglobulin E (p = 0.001) and interleukin-4 (p < 0.05) than those without antibodies." (PMID 15710045, 2005).
asthma (continued). "For example, genes in the 5q31-5q33 region code for Th2-type cytokines (IL-4, IL-13, which regulate B cell heavy-chain class-switching to IgE production) and ADRB2 (which mediates airway smooth muscle relaxation and protects against bronchial hyperreactivity)." (PMID 15339344, 2004). "Asthma accompanied by Type 2 inflammation primarily involves the stimulation of Th2 cells and Type 2 innate lymphoid cells (ILC2) in response to allergens and viruses, leading to the secretion of Type 2 cytokines including IL‐4, IL‐13, and IL‐5 (interleukin‐5)." (PMID 41568067, 2026). "Since both IL-4 and IL-13 contribute to a positive feedback loop that promotes TSLP expression, inhibition of their signaling by dupilumab may help mitigate inflammation during virus-induced asthma exacerbations by indirectly reducing TSLP production." (PMID 41576028, 2026). "Patients with severe asthma are refractory to inhaled corticosteroids and the majority are characterized by eosinophilic airway inflammation (sputum or bronchoalveolar lavage [BAL]), with elevated exhaled nitric oxide (FeNO), and Type 2 gene signatures (IL‐4, ‐5 and ‐13)." (PMID 39358991, 2025). "By mitigating airway hyperreactivity, reducing the levels of inflammatory cytokines (IL-4, IL-5 and IL-13) involved in the Th2 immune response, and enhancing Treg immune regulation (IL-10 and TGF-β1), hydrogen therapy has emerged as a promising adjunct strategy in asthma management." (PMID 41146240, 2025). "However, the levels of IFN-γ, IL-10, and type-2 cytokines, including IL-4, IL-5, and IL-13, were not significantly different between Sema3E KO and WT mice in the type-2 low asthma model." (PMID 40512736, 2025). "While IL-4–induced type 2 inflammation is rare in viral disease, it is not unprecedented that IL-4 plays a role in viral inflammation for example in RSV infection in which RSV G protein preferentially induces a Th2 response contributing to asthma exacerbations." (PMID 40854598, 2025). "Similarly, increases in classic asthma-driving cytokines were modest (IL-4, IL-5) or absent (IL-13)." (PMID 39229121, 2025). "Despite a trend for CCL17 protein being higher in these two participants, all other macrophage responses to IL-4, IL-13, and combined IL-4/IL-13 stimulation fell within the range of responses seen in donors without asthma and did not skew the overall dataset, justifying their inclusion." (PMID 41159038, 2025). "While several clinical studies have observed dysregulated miR-21 levels in exosomes or serum of asthmatic patients, showing correlations with disease severity such as IgE, IL-4, and lung function, no clinical trials have yet tested miRNA-based therapeutics in asthma." (PMID 40806756, 2025). "Hence, in our mouse model of asthma, major indicators relating to the asthma model (e.g., airway hypersensitivity, total serum IgE, IFN-γ, IL-4, IL-10, IL-13, and inflammatory cell count in BALF) were detected to evaluate the physiological and biochemical changes induced by the antigen (OVA)." (PMID 38674852, 2024). "However, the significance of IFN-γ and IL-4 in children with MP infection-related asthma is not fully elucidated." (PMID 39572779, 2024). "However, the Dex-treated group was no different from the OVA-induced asthma group with regard to IL-4 levels." (PMID 38675190, 2024). "In addition, histamine is found to promote IL‐10 and inhibit TGF‐α in OVA‐induced asthma in mice, thereby reducing the total number of cells in bronchoalveolar lavage fluid (BALF) and the number of inflammatory factors such as IL‐4, IL‐5, and IL‐13 in lung tissue." (PMID 38687096, 2024). "Furthermore, individuals with depression have significantly higher levels of inflammatory cytokines, such as interleukin-1 (IL-1), interleukin-4 (IL-4), interleukin-6 (IL-6), and tumor necrosis factor-alpha (TNF-α), which are also important mediators in the pathogenesis of asthma." (PMID 39479594, 2024).
asthma (continued). "Our findings have revealed that obese asthma patients, despite the basic anti-inflammatory therapy, had elevated levels of inflammatory markers in blood plasma such as leptin, tumor necrosis factor-α (TNF-α), interleukin-2 (IL-2), IL-4, and IL-17a, leukotriene B4 (LTB4), and thromboxane B2 (TXB2)." (PMID 37367676, 2023). "Eosinophilia can identify asthmatic patients who may benefit more significantly from ICS therapy, and monoclonal antibodies targeting IgE or the type 2 cytokines (IL‐4, IL‐5 and IL‐13) or alarmins (IL‐33, TSLP) benefit patients with the ‘Type‐2‐high’ phenotype of asthma." (PMID 37963721, 2023). "However, OS biomarkers NO2−, lipid peroxide, protein sulfhydrils, and inflammatory biomarkers TNFα, IL-4, IL-37, IL-1β, IL-1RL1, IL-1R1, NLRP3, and TGF-β1 showed positive association with asthma in nonsmokers, but not in smokers." (PMID 37367073, 2023). "Beyond asthma, GERD was also identified as a predictor of biologic use, possibly relating to increased likelihood of type 2 inflammation (i.e., eosinophilia and high levels of interleukin-4/5/13) and therefore biologic selection, in patients with CRSwNP and GERD." (PMID 38066550, 2023). "Results of Elisa revealed that there was a statistically significant decrease in INF-γ expression and an increase in IL-4, IgE, IL-17 levels, which suggesting that inulin intake during pregnancy improves lung inflammation in offspring with asthma, and this effect that is independent of gender." (PMID 37014871, 2023). "The underlying mechanisms of BA in the treatment of immune modulation on PF and asthma manifest as the regulation of Th17/Treg responses by promoting Treg cell differentiation, inhibiting the expression of Th17A, and reducing the levels of IL-6, IFN-γ, IL-4, and IL-23." (PMID 37007037, 2023). "In T2-high asthma, the interaction of the airway epithelium with the external exposome activates the release of specific mediators—epithelial-derived alarmins—as thymic stromal lymphopoietin (TSLP), IL-25, and IL-33, leading to the production of IL-4, IL-5, and IL-13." (PMID 37761964, 2023). "Specifically, in an OVA-induced murine asthma model, intranasal treatment with a polyclonal rabbit anti-ALCAM antibody at the time of OVA challenge reduced allergic symptoms, such as the leukocyte count and Th2 cytokine (i.e., IL-4, IL-5, and IL-13) levels in BAL fluid." (PMID 37514028, 2023). "Our experimental results indicated that MS ameliorated asthma-induced AHR and decreased cellular infiltration in the lung epithelium, decreased EOS cell counts in BALF and the lungs, lowered proinflammatory CK (IgE, IL-4, and IL-5), and augmented anti-inflammatory CK (IL-10) expression." (PMID 35812246, 2022). "Compared with the model group, Danlong Dingchuan Decoction effectively reduced the expression levels of TNF-α, IL-4, TGF-β1, IL-6, IL-8, and IL-1β in the lung tissue, reduced the release of inflammatory factors, alleviated airway inflammatory response, and relieved asthma symptoms." (PMID 35186104, 2022). "While such insight may not impact ongoing attempts to target IL-4 and IL-13 in treatment of asthma, it could prompt further studies into B cell-directed therapies for allergic disease." (PMID 35359977, 2022). "IL-4-producing CD8+ T cells have been suggested to be noncytolytic helper cells that do not produce IFN-γ, associated with humoral immunity in old age, asthma in children, and autoimmune arthritis." (PMID 35273611, 2022). "A correct definition of asthma and CRS phenotype/endotype is crucial, taking into account the availability of novel biological therapies, such as anti-IgE, anti-IL-5/IL-5Rα and anti-IL4/IL-13Rα, which are dedicated to patients who do not respond to conventional asthma or CRSwNP therapies." (PMID 33805199, 2021).
asthma (continued). "Here, we develop conjugate vaccines against mouse IL-4 and IL-13, and demonstrate their prophylactic and therapeutic efficacy in reducing IgE levels, AHR, eosinophilia and mucus production in mouse models of asthma analyzed up to 15 weeks after initial vaccination." (PMID 33976140, 2021). "In a rat model of asthma induced by OVA, O. basilicum hydroethanolic extract (0.75, 1.50, and 3.00 mg/ml) in drinking water, for 21 days during the sensitization period, reduced IL-4, PLA2, IgE, and total protein (TP) levels but enhanced the IFN-γ/IL-4 ratio in a dose-dependent manner." (PMID 35046828, 2021). "However, it should be mentioned that under certain conditions, breast milk contains allergens and cytokines (IL-4, IL-5, IL-13, TGF-β, etc.)that might contribute to the development of asthma and airway wall remodeling." (PMID 34834581, 2021). "Furthermore, it decreased OVA-specific IgE and IL-4 levels in serum, relieved airway remodeling, attenuated subepithelial collagen deposition, and downregulating TGF-β1and Smad3 expression in mice with asthma." (PMID 34804018, 2021). "Furthermore, conjugate vaccines against IL4 failed to reduce mucus production in murine model of asthma induced by HDM, as opposed to ones directed against IL13 that abrogated mucus production in the lung bronchial epithelium." (PMID 34305924, 2021). "The numbers of inflammatory cells and the levels of T2 cytokines (IL-4, IL-5, IL-13, and IL-33) in BALF were increased in the LTE4-alone, OEA-alone, and LTE4-pretreated groups, and these factors play important roles in airway inflammation and asthma remodeling." (PMID 34079051, 2021). "Another limitation of using gene expression profiling of selected cytokines (IL4, IL5, and IL13) in induced sputum for asthma stratification in comparison to unsupervised approaches employing several biomarkers is that prevalence of T2-high asthma might be underestimated." (PMID 33513844, 2021). "In fact, an in vitro study showed that retinoic acid reduced IL-4-induced eotaxin expression in human bronchial epithelial cell line BEAS-2, suggesting that retinoic acid may reduce eosinophilic airway inflammation in diseases such as asthma." (PMID 34436475, 2021). "Recent and ongoing trials for asthma may open new possibilities for EGPA treatment: dupilumab is a fully human monoclonal antibody that binds to the alpha subunit of the IL-4 receptor, inhibiting the activity of both IL-13 and IL-4." (PMID 34796188, 2021). "Interestingly, the level of T-bet mRNA and IFN-γ+ T cells does not reduce in the asthma model, which is likely to be adjusted spontaneously against the increasing number of IL-4+ T cells in asthmatic mice." (PMID 32489402, 2020). "This study revealed that PCF can downregulate ERK and Toll-2 and upregulate IDO and Toll-9 expression, reduce IL-4 level, and increase IL-12, IFN-α, and IFN-r in BALF, thus restoring the balance of T cells via TLRs and DCs to improve airway inflammation and reduce asthma symptoms." (PMID 32953887, 2020). "Some C3 proteins are highly associated with asthma, such as: CD80 influences synthesis of IL-4 and IFN in non-specific bronchial asthma, mutations in IL12A influence cockroach allergy among children with asthma, ADA polymorphisms are related to asthma." (PMID 33008305, 2020). "However, the role of Tespa1 in the IL-4/STAT6 signaling pathway, an important pathway for mast cell function and asthma pathogenesis, remains unclear." (PMID 33228696, 2020). "We have previously demonstrated NFATc1 messenger RNA (mRNA) induction in peripheral blood mononuclear cells (PBMCs) in pediatric asthma and that the absence of NFATc1 in T cells results in the downregulation of IL‐4 and other Th2 cytokines and IgE in asthma models." (PMID 33079489, 2020).
asthma (continued). "However, emerging evidence suggests that T follicular helper (TFH) cells, rather than TH2 cells, predominantly produce IL-4 and IL-21 in B cell follicles and closely regulate IgE class-switching during severe asthma development in both mice and humans." (PMID 31921177, 2019). "In addition, IL4, IL8 and TNFα have been related with the pulmonary function in obstructive airway diseases and could be potential markers of asthma." (PMID 30986261, 2019). "In view of blocking IL-13 alone is possibly not enough to achieve asthma control because of the overlapping pathophysiological roles of IL-13/IL-4 in inflammatory pathways, combined blocking of IL-13 and IL-4 with monoclonal antibodies may be more encouraging." (PMID 30703143, 2019). "However, it is not easy to induce BEAS-2B cells to express eotaxin using TNF-α, and previous experiments showed that TNF/IL-4 could stimulate BEAS-2B cells to express eotaxin, which attracted eosinophils into allergic airways and lung tissue in asthma." (PMID 29962952, 2018). "Thanks to this kind of studies, we know now that bronchial neutrophilia in bronchoalveolar lavage fluid is associated with severe asthma independent of oral corticosteroid intake, as well the elevated CD4+ cells expressing both IL-4 and IL-17 predicted greater asthma severity." (PMID 30598830, 2018). "Furthermore, they also demonstrated that VCAM-1, but not E-selectin or ICAM-1, is significantly increased in IL-4-positive asthma patients, compared with IL-4-negative asthma patients." (PMID 29614819, 2018). "Cytokines including interleukin 4 (IL-4), interleukin 5 (IL-5), IL-6, IL-8, interleukin 10 (IL-10), monocyte chemoattractant protein (MCP)-1/CCL2, and thymus and activation-regulated chemokine (TARC)/CCL17 trigger secondary inflammatory events, aggravating asthma pathogenesis." (PMID 29755573, 2018). "Similar to our previous study showing that bvPLA2 was effective in decreasing Th2 cytokine expression in an asthma mouse model, treatment of WT mice with bvPLA2 following DFE/DNCB exposure significantly decreased the expression of Th1 and Th2 cytokines including IFN-γ, IL-4, IL-6, and IL-10." (PMID 29614845, 2018). "In conclusion, elevated serum levels of IL-4 and increased expression of GATA3 and GATA3/FOXP3 ratio in PBMCs isolated from patients with asthma indicate an imbalance in the levels of Th2/Treg-related transcription factors and a Th2-deviated pattern in patients with asthma." (PMID 30116273, 2018). "Thus the addition of CXCL-1, IFN-γ, IL-5, IL-17A, EGF, eotaxin, IL-lβ, IL-4, IL-12p40, IL-13, and MDC serum concentrations to blood eosinophils and neutrophils adds significant value to the definition of the Difficult-to-Control asthma endotype." (PMID 28686637, 2017). "The experimental model for the induction of asthma has increased cellularity in the BAL represented by eosinophils, lymphocytes and neutrophils, as well as an increase in cytokines with a Th2 profile (IL-4 and IL-5), together with the production of mucus in the airways." (PMID 29145431, 2017). "However, there were no significant changes in IFN-γ, FOXP3, and IFN-γ/IL-4 ratio in asthma group treated with dexamethasone compared with untreated asthma group." (PMID 28824424, 2017). "The treatment with recombinant mouse B7-H3 significantly increased the IL-4 (29.34 ± 4.67 pg/mL), IL-5 (17.64 ± 0.84 pg/mL), IL-13 (421.31 ± 53.60 pg/ml) and IFN-gamma (266.01 ± 32.72 pg/ml) concentration in BALF as compared with mice in the wild-type group with asthma (P < 0.05)." (PMID 28094276, 2017). "Previously, Jung and colleagues found that KWG could inhibit the infiltration of inflammatory cells in ovalbumin (OVA)-induced allergic mouse model of asthma, and decrease OVA-specific IgE and IL-4, IL-5, and IL-13 in the sera and bronchoalveolar lavage fluids." (PMID 27879681, 2016).